TAP1 (transporter 1, ATP binding cassette subfamily B member)
Diseases named in the same sentence as TAP1 in open-access papers (continued):
Sharing a sentence is not in itself a finding about the gene and the disease.
pancreatic adenocarcinoma (5 papers, 2020 to 2023). "TAP1 as the downstream target of SHH signaling enhances the drug resistance in pancreatic adenocarcinoma, providing a promising therapeutic approach for the development of more effective targeted therapies in the treatment of PDAC patients." (PMID 36419887, 2022). "To investigate the clinical relevance of TAP1 in human pancreatic cancer patients, we analyzed the expression of TAP1 in pancreatic adenocarcinoma cohort from TCGA." (PMID 35806187, 2022). "Patients with low expression levels of TAP1 (z-score < −0.5) showed better overall survival rate and disease-free survival rate than patients with high expression levels of TAP1 (z-score > −0.5), suggesting that TAP1 exerted a cancer-promoting role in pancreatic adenocarcinoma." (PMID 35806187, 2022). "Among tumors, TAP1 showed marked overexpression in cervical and endocervical cancers (CESC) and HNSC, relative to other tumors, while the greatest difference between normal and corresponding malignant tissues was detected in cholangiocarcinoma (CHOL), GBM, and pancreatic adenocarcinoma (PAAD)." (PMID 36759763, 2023).
tuberculosis (5 papers, 2013 to 2026). A chronic, recurrent infection caused by the bacterium Mycobacterium tuberculosis. "Mutations in additional ECM increased genes such as Tap1 and B2m also cause susceptibility to tuberculosis, while their direct effects on ECM susceptibility have yet to be tested." (PMID 23853600, 2013). "Tuberculosis (TB) is a common infectious disease, and the present study aims to explore the associations of single nucleotide polymorphisms (SNPs) at rs1135216 and rs1057141 of transporter-associated antigen processing (TAP1) and rs2228396 of TAP2 with pulmonary tuberculosis (PTB) risk." (PMID 33736739, 2021). "Finally, we demonstrate that TB10.4-specific CD8+ T cells mediate protection against tuberculosis, which requires interferon-γ production and TAP1-dependent antigen presentation in vivo." (PMID 25945999, 2015).
type 1 diabetes (5 papers, 2014 to 2020). "Transporter associated with antigen processing 1 (TAP1) I333V gene polymorphism has been suggested to be associated with type 1 diabetes mellitus (T1DM) susceptibility." (PMID 24655325, 2014). "Anomalies in TAP1 and PSMB proteins have been reported to be associated with vitiligo along with several other AIDs such as Sjogren’s syndrome, type 1 diabetes, juvenile rheumatoid arthritis, celiac disease, and multiple sclerosis." (PMID 28129744, 2017). "The genetic control of insulin-dependent diabetes mellitus (IDDM) mainly depends on the HLA gene in the MHC, while the TAP1 gene is involved in its regulation, andTT TAP1 may induce insulin-dependent diabetes mellitus." (PMID 30131712, 2018). "For example, certain polymorphisms of the transporter associated with antigen processing (TAP1 and TAP2) and the immunoproteasome subunits LMP2 and LMP7, both involved in MHCI antigen presentation, have been linked to type 1 diabetes (T1D) by genetic association studies." (PMID 27534821, 2016). "Several reports have described genetic associations of TAP1 and TAP2 polymorphisms with autoimmune/inflammatory diseases including systemic lupus erythematosus, hypersensitivity pneumonitis, vitiligo, Graves’ disease, type I diabetes, systemic sclerosis, and ankylosing spondylitis." (PMID 31732831, 2020).
uveal melanoma (5 papers, 2020 to 2025). A melanoma derived from melanocytes of the uveal tract. "Notably, some cancer types were observed to only have one type of TAP1 genetic alteration; for example, esophageal adenocarcinoma and uveal melanoma (UVM) only exhibited amplification, while mutation was the sole alteration type in thymoma (THYM)." (PMID 36759763, 2023). "This study investigated the transcriptional expression profile of TAP1 in uveal melanoma (UVM), revealed its potential biological interaction network, and determined its prognostic value." (PMID 36774490, 2023). "No previous study has investigated TAP1 expression in uveal melanoma." (PMID 36774490, 2023).
vitiligo (5 papers, 2014 to 2025). Generalized well circumscribed patches of leukoderma that are generally distributed over symmetric body locations and is due to autoimmune destruction of melanocytes. "Association of PSMB8 and TAP1 polymorphisms in patients with active and stable vitiligo from Gujarat." (PMID 28700671, 2017). "Several studies have addressed the association of PSMB8 and TAP1 polymorphisms in patients with vitiligo; however, studies revealing the impact of these polymorphisms at transcript and protein levels are few." (PMID 28700671, 2017). "Out of 8 different single nucleotide polymorphisms (SNPs) of PSMB and TAP gene region studied, PSMB8 intron 6 G/T and TAP1 exon 10 A/G were found to be significantly associated with vitiligo in the Western population." (PMID 28700671, 2017). "Distribution of haplotypes frequencies for PSMB8 (C/T) and TAP1 (A/G) polymorphisms in vitiligo patients and controls." (PMID 28700671, 2017). "Association of PSMB8 and TAP1 polymorphisms in patients with vitiligo from Gujarat." (PMID 28700671, 2017). "In contrast, two studies have found TAP1 exon 10 SNP to be associated with vitiligo in Saudi population, and this may be due to differences in the ethnicity." (PMID 28700671, 2017). "Here, we report the findings of a study to further investigate the associations between TAP1/PSMB genetic variants and vitiligo in Saudi patients and to evaluate the influence of genotypes on risk and severity of disease." (PMID 25548428, 2014). "The TAP1-rs1135216 and PSMB9-rs17587 mutant alleles were strongly associated with vitiligo, with odds ratios showing five fold and two fold risks (P < 0.0001 and P = 0.007, resp)." (PMID 25548428, 2014). "The TAP1 637G and PSMB9 60H mutant alleles were found to significantly increase the risk of vitiligo (fivefold and twofold, resp)." (PMID 25548428, 2014). "In conclusion, the TAP1-rs1135216 and PSMB9-rs17587 variants are significantly associated with vitiligo, and even one copy of these mutant alleles can influence the risk among Saudis." (PMID 25548428, 2014). "Another study showed significant association of TAP1 exon 10 A/G polymorphism with vitiligo in Saudi population but not for PSMB8 intron 6 G/T polymorphism." (PMID 28700671, 2017). "However, further replicative studies and in vitro functional studies for PSMB8 and TAP1 are needed to delineate the role of defective antigen processing and presentation pathways in vitiligo pathogenesis." (PMID 28700671, 2017). "An earlier study in Caucasians revealed a significant association between vitiligo and TAP1-rs1135216 (P = 0.0034) but a nonsignificant result between vitiligo and PSMB9-rs17587 (P = 0.11)." (PMID 25548428, 2014). "We evaluated whether TAP1-rs1135216 (p.637D>G) and PSMB9-rs17587 (p.60R>H) were significantly associated with the risk and severity of vitiligo among Saudi patients." (PMID 25548428, 2014). "However, despite having high prevalence of vitiligo in Gujarat, there are no reports of PSMB8 and TAP1 polymorphisms so far." (PMID 28700671, 2017).
atherosclerosis (4 papers, 2007 to 2020). A disease characterized by the build-up of fatty material and calcium deposition in the arterial wall resulting in partial or complete occlusion of the arterial lumen. "Although CD8+ T cells in TAP1-deficient mice are known to be functional, the effector cell- and regulatory T cell population here was still smaller than in Apoe−/− mice, giving them a limited impact on atherosclerosis." (PMID 22479479, 2012). "Surprisingly, the Apoe−/−Tap1−/− mice developed lesions of the same size as the Apoe−/− mice, indicating that TAP1-deficiency has no or minor effect on atherosclerosis." (PMID 22479479, 2012). "Thus, the similar lesion size in Apoe−/− mice and Apoe−/−Tap1−/− mice reflects a minor role of TAP1 for atherosclerosis development." (PMID 22479479, 2012). "Moreover, the macrophage lesion infiltration was not affected indicating that TAP1 deficiency does not exert major APC-driven effects on atherosclerosis progression." (PMID 22479479, 2012). "Taken together, the present study provides novel information indicating a limited role of TAP1 and CD8+ T cells in atherosclerosis development." (PMID 22479479, 2012). "In conclusion, Apoe−/−Tap1−/− mice develop atherosclerosis equal to Apoe−/− mice, indicating a minor role for CD8+ T cells and TAP1-dependent antigen presentation in the disease process." (PMID 22479479, 2012). "A neutral or protective action is supported by unaltered atherosclerosis in ApoE−/− mice lacking antigen peptide transporter 1-(TAP1)-dependent MHC-I antigen presentation, despite the low number of CD8+ T cells in these animals." (PMID 31653058, 2019).
breast tumor (4 papers, 2014 to 2022). "Low or defective TAP1 in breast tumors predicts higher risks for developing metastasis and down-regulation of the interferon-stimulated genes IFIT1 and MX1 has been linked to immune evasion mechanisms and tumor progression." (PMID 24870930, 2014). "In ER+ breast tumor, we found that patients who did not respond to therapy showed a higher expression of TAP1 and TP53I3 compared with responders." (PMID 34109737, 2022). "TAP1 expression levels were low to negative in stage I breast tumors." (PMID 29091951, 2017).
metastatic tumors (4 papers, 2017 to 2024). "Higher level of TAP1 in metastatic tumors were associated with higher levels of vimentin and LEF1, while associated with lower level of E-cadherin." (PMID 34957213, 2021). "Intriguingly, we also found that the TAP-1 deficiency was not regulated by mutations or other defects in the TAP-1 gene in many metastatic tumours, but it was epigenetically regulated and could be restored by treatment with HDAC inhibitors, such as trichostatin-A (TSA)." (PMID 37637416, 2023). "Analyses of patient data from the Cancer Genome Atlas (TCGA) showed that GIMAP6, SAMD9L, and IL27 are significantly upregulated in metastatic tumors compared to the primary lesions, whereas TAP1 was not differentially expressed in patient samples." (PMID 38719996, 2024).
pancreatic cancer (4 papers, 2020 to 2025). "A gene screening of 23 ABC transporters identified a marked increase in TAP1 expression in the gemcitabine-resistant variants of pancreatic cancer cells." (PMID 35806187, 2022). "In our study, we observed that a subtype of KRAS-mutant pancreatic cancer cells with higher expression of TAP1 were more resistant to MEKi." (PMID 35806187, 2022). "Together, our results suggest that TAP1 expression enhanced the stemness of pancreatic cancer cells." (PMID 35806187, 2022).
primary immunodeficiency (4 papers, 2020 to 2024). "TAP1 deficiency, an exceedingly rare primary immune-deficiency disorder, presents with severe chronic sino-pulmonary infection and cutaneous granulomas." (PMID 38680488, 2024). "According to the GSEA analysis, multiple immunity-related signaling pathways, such as primary immunodeficiency, DNA replication, and the cell cycle of the Toll-like receptor signaling pathway, were enriched alongside elevated TAP1 expression." (PMID 36774490, 2023). "According to GSEA analysis, various immunity-related signaling pathways such as primary immunodeficiency were enriched in the presence of elevated TAP1 expression." (PMID 36774490, 2023). "An equally high overrepresentation (OVF = 20.83, q-value = 2.38 × 10−6) was determined for the “magenta” module that was enriched in genes that control primary immunodeficiency, including ADA, CD19, CD79A, IGLL1, TAP1, TAP2, TNFRSF13C, and ZAP70." (PMID 32873298, 2020).
asthma (3 papers, 2017 to 2022). "Studies on the polymorphisms of the TAP1 gene in several human leukocyte antigen (HLA)-associated diseases such as atopic dermatitis, asthma, rhinitis found that rs1057141 and rs1135216 as the most common single nucleotide polymorphisms." (PMID 29416713, 2018). "Subgroup analysis by atopic types indicated significant association of TAP1 polymorphism rs1135216 with asthma in the allele, dominant and recessive models and with allergic rhinitis in the recessive model." (PMID 29416713, 2018). "Three distinct transcriptional asthma phenotypes (TAPs) were identified that had similarities to previously defined sputum inflammatory phenotypes of eosinophilic (TAP1), neutrophilic (TAP2), and paucigranulocytic (TAP3) asthma." (PMID 29018800, 2017). "A recent study reported colocalizations between eQTLs for HLA-B, HLA-DQB1, HLA-DQA1, HLA-DRA, TAP1, and RNF5 in induced pluripotent stem cells with asthma GWAS SNPs." (PMID 35606880, 2022).
celiac disease (3 papers, 2017 to 2022). An autoimmune genetic disorder with an unknown pattern of inheritance that primarily affects the digestive tract. "The most significantly up-regulated genes in celiac disease were TAP1, HLA-E, HCP5, STAT1, GBP1, STAT1, LOC100419583, and GBP4 and the down-regulated ones were IDS, PKIB, FBXO2, OXT, and ADI1." (PMID 36011206, 2022).
clear cell renal cell carcinoma (3 papers, 2022 to 2025). "Therefore, it’s significant to clarify the role of TAP1 in clear cell renal cell carcinoma (ccRCC)." (PMID 36419887, 2022).
diabetes (3 papers, 2014 to 2024). "Among the associations only found in participants with diabetes, a TAP1 gene variant was associated with DBP." (PMID 39258111, 2024).
endometrial cancer (3 papers, 2016 to 2024). Primary or metastatic malignant neoplasm involving the endometrium (mucous membrane that lines the endometrial cavity). "The findings on protein expression were validated using RNAseq data of TCGA MSI endometrial cancers, except for TAP1." (PMID 27213585, 2016). "Moreover, our results showed that TAP1 expression levels were increased in gynecological tumors, including OC, CC, and endometrial cancer." (PMID 34957213, 2021). "The functional implication of JAK1 in tumor immune evasion was analyzed by expression analysis of TAP1, LMP7, HLA class I and presence of CD8-positive T-cells in the MSI endometrial cancers." (PMID 27213585, 2016). "The 13 JAK1 mutant endometrial cancers showed significantly lower expression of TAP1 (2.1-fold, P<0.001), LMP7 (3.0-fold, P<0.001), and HLA class I (2.5-fold, P<0.001) in comparison to JAK1 wildtype endometrial cancers." (PMID 27213585, 2016).
head and neck squamous cell carcinoma (3 papers, 2018 to 2020). A squamous cell carcinoma that arises from any of the following anatomic sites: lip and oral cavity, nasal cavity, paranasal sinuses, pharynx, larynx, and salivary glands. "To independently evaluate the prognostic value of TAP1, we downloaded gene expression and clinical data from The Cancer Genome Atlas, TCGA,-head and neck squamous cell carcinoma (HNSC) cohort." (PMID 32867395, 2020).
Immunodeficiency (3 papers, 2020 to 2022). Failure of the immune system to protect the body adequately from infection, due to the absence or insufficiency of some component process or substance. "The hub genes of this gene set were all critical genes involving the T cell signaling (LCK), antigen translocation (TAP1), and immunodeficiency diseases (JAK3 and RAG1)." (PMID 36180885, 2022). "Patient K207 was a 12-year-old boy with immunodeficiency in MHC class I complex and a confirmed mutation in the TAP1 gene." (PMID 33810069, 2021). "Additionally, some genes involved in our signature, such as TAP1 and NGF, are linked to immunodeficiency 44, 45, whose mutations may destroy the immune system and drive the aberrant mutation accumulation in somatic cells." (PMID 31949492, 2020).
non-small cell lung carcinoma (3 papers, 1996 to 2024). A group of at least three distinct histological types of lung cancer, including non-small cell squamous cell carcinoma, adenocarcinoma, and large cell carcinoma. "TAP1 expression was stronger in the non-small cell lung cancer (GSE99254), liver hepatocellular carcinoma (LIHC; GSE98638), and CRC (GSE108989) datasets than in other cell lines." (PMID 36759763, 2023).
pancreatic ductal adenocarcinoma (3 papers, 2020 to 2022). An infiltrating adenocarcinoma that arises from the epithelial cells of the pancreas. "Suppression of TAP1 significantly sensitized the MEKi-resistant pancreatic ductal adenocarcinoma (PDAC) cells to MEKi and induced higher apoptotic rate in vitro." (PMID 35806187, 2022). "ABCB2 (TAP1) is regarded as the downstream target of SHH signaling and plays an important role in enhancing the drug resistance of pancreatic ductal adenocarcinoma." (PMID 33393862, 2021).
prostate adenocarcinoma (3 papers, 2021 to 2023). "TAP1 was positively correlated with DMNT1 in OC, CESC, PAAD, pheochromocytoma and paraganglioma; (PCPG), prostate adenocarcinoma (PRAD), STAD, UVM, BLCA, BRCA, COAD, DLBC, HNSC, kidney chromophobe (KICH), KIRC, KIRP, LAML, LGG, and LIHC (p < 0.05)." (PMID 34957213, 2021). "Pan-cancer analysis indicated that TAP1 expression was positively correlated with immune regulators in the majority of cancer types, particularly BRCA, KIRC, prostate adenocarcinoma (PRAD), testicular cancer (TGCT), thyroid carcinoma (THCA), and UVM." (PMID 36759763, 2023).
prostate carcinoma (3 papers, 2014 to 2021). A carcinoma that arises from epithelial cells of the prostate gland. "In contrast, high frequencies of loss or downregulation of low molecular weight polypeptides 2 (LMP2), transporters associated with antigen processing 1 (TAP1), and tapasin as well as of β2-microglobulin were demonstrated in prostate cancer when compared to normal prostate tissue." (PMID 24772169, 2014). "We demonstrated DNA demethylation of the promoter sequences of selected antigen-presenting machinery genes (TAP-1/LMP-2, TAP-2) upon IFNγ treatment both in the MHC class I-deficient tumour cell line TC-1/A9 and in the prostate cancer cell line TRAMP-C2." (PMID 25071011, 2014).
serous ovarian cancer (3 papers, 2018 to 2021). "Further, we have constructed an immune-related risk model based on TAP1 and CXCL13 for the first time to predict the prognostic response of advanced serous ovarian cancer." (PMID 34631788, 2021). "In this study, we screened the immune-related genes of serous ovarian cancer from a different perspective and discovered the importance of TAP1 and CXCL13 as independent prognostic and predictive markers for serous ovarian cancer." (PMID 34631788, 2021).
small cell lung carcinoma (3 papers, 2021 to 2023). Small cell lung cancer (SCLC) is a highly aggressive malignant neoplasm, accounting for 10-15% of lung cancer cases, characterized byrapid growth, and early metastasis. "TAP1 was involved in IL-27-mediated anti-PD-1 antibody immunotherapy in small cell lung cancer." (PMID 34957213, 2021).
thyroid carcinoma (3 papers, 2020 to 2023). "TAP1 was positively correlated with ESTIMATE scores in CESC (R = 0.493, p < 0.0001), OC (R = 0.448, p < 0.0001), UVM (R = 0.667, p < 0.0001), testicular germ cell tumors (TGCT) (R = 0.805, p < 0.0001), and thyroid carcinoma (THCA) (R = 0.743, p < 0.0001), etc.." (PMID 34957213, 2021).
cervical intraepithelial neoplasia (2 papers, 2015 to 2024). "HPV-infected patients with single-nucleotide polymorphisms (SNPs) detected in one or two alleles in the TAP1 gene have a reduced risk of high-grade cervical intraepithelial neoplasia (HGCIN), and hence require less frequent follow-ups." (PMID 38611599, 2024).